INS (insulin)
Diseases named in the same sentence as INS in open-access papers (continued):
Sharing a sentence is not in itself a finding about the gene and the disease.
diabetes (continued). "As demonstrated by the results to date of the 4T program, the CDCES can work at the top of their certification, following a policy to make insulin dose adjustments without decreasing safety (increasing hypoglycemia), thus assisting the person with diabetes in reaching and maintaining target goals." (PMID 41283065, 2025). "While evidence suggests potential benefits in improving insulin sensitivity, glucose metabolism, and glycemic control, these natural compounds should not replace insulin or prescribed diabetes medications without thorough clinical validation and direct recommendations from healthcare professionals." (PMID 40563946, 2025). "EGR1 and EGR2 play a key role in insulin signaling and lipid metabolism and have been involved in adipocyte differentiation programs, and RREB1 has been shown as novel candidate gene for diabetes affecting insulin sensitivity, beta-cell function and adipogenesis." (PMID 40646607, 2025). "Improving insulin sensitivity to modulate TTN stiffness, through targeting neuroregulin-1 or via treatment with metformin, reverses the altered phosphorylation of the N2B and PEVK domains found in diabetes patients, showing its therapeutic potential for diastolic dysfunction." (PMID 41465209, 2025). "However, there are several studies that support the fact that most children and adolescents with diabetes have suboptimal glycemic control regardless of the type of sensor and insulin delivery device." (PMID 40863228, 2025). "Clinical clues, such as an early age at onset, the absence of autoantibodies, atypical disease progression, low insulin requirements, and the presence of multi-organ involvement, may indicate a non-classical diabetes phenotype." (PMID 41323015, 2025). "Furthermore, among patients with diabetes, the prevalence of sarcopenia was 22.5% in those not receiving insulin, compared with 75.0% in those treated with insulin." (PMID 41464593, 2025). "Despite a marked improvement in insulin sensitivity in the trained leg in both groups, a specific induction in genes involved in glycogen breakdown and glycolysis in type IIA myonuclei was seen only in the control group, while this response was blunted in the diabetes group." (PMID 40413649, 2025). "However, a long-term increase in lipid compounds leads to initial insulin resistance in peripheral tissues, which is in the early stage of the disease, and the body has not yet developed diabetes." (PMID 40070584, 2025). "However, individuals in early stage 3 (glucose levels consistent with the definition of diabetes mellitus) do not immediately require insulin." (PMID 40316962, 2025). "Basal insulin and high-concentration pre-meal injections are insufficient for adequate blood glucose management in diabetes because they may not provide long-term stability." (PMID 41294766, 2025). "We hypothesized that genetically driven insulin hypersecretion in diffuse CHI might lead to β-cell degranulation followed by dedifferentiation and transdifferentiation, as previously demonstrated in β-cells exposed to hyperglycemia in diabetes models." (PMID 41598174, 2025). "During the postoperative follow-up, one patient developed new-onset diabetes post-surgery, one diabetic patient achieved remission without requiring exogenous hypoglycemic drugs or insulin, and two (3.2%) patients still required oral pancreatic enzyme supplementation 6 months post-surgery." (PMID 39710806, 2025). "As a model of nonobese T2DM, the STZ + NAA system has distinct advantages for diabetes research: it maintains stable moderate hyperglycemia without requiring exogenous insulin for animal survival, retains partial glucose-stimulated insulin secretion capacity, and responds to sulfonylureas." (PMID 41234228, 2025). "For example, the scale does not include diabetes-specific metabolic indicators (such as glucose variability coefficient and insulin requirements), which may lead to an underestimation of the nutritional risk in these patients." (PMID 40585912, 2025).
diabetes (continued). "Notably, INS and GCG, levels were significantly decreased in donors with PDAC-associated diabetes compared to those with PDAC but no diabetes." (PMID 40244011, 2025). "Diabetes mellitus (DM) represents a multifactorial metabolic disorder marked by persistent hyperglycemia, which occurs either due to a lack of insulin (type 1 diabetes, T1DM) or to insulin resistance combined with insufficient insulin production (type 2 diabetes, T2DM)." (PMID 40299501, 2025). "Second, the absence of a diabetic group treated with insulin precludes direct comparison of L-carnitine’s efficacy with standard diabetes management, which could provide valuable clinical context." (PMID 41408003, 2025). "The strengths of this study include the use of validated calculated biomarkers for the endotypes of insulin–glucose homeostasis, the stratification for the severity of inflammation and the comparison with a group of unaffected persons without HS and/or diabetes." (PMID 40217596, 2025). "The fact that we did not observe changes in insulin levels in our studies, or changes in glucose after glutamine challenge suggests that these indirect effects are insufficient on their own to produce diabetes." (PMID 40675550, 2025). "Based on our results we hypothesise that such a decline is reached earlier in pregnancies where the mother has diabetes than in pregnancies without diabetes due to increased insulin-mediated placental growth." (PMID 41282652, 2025). "Similarly, although OGTT is the gold standard for diabetes diagnosis, it reflects only a single time point of glucose metabolism and fails to account for fluctuations in insulin sensitivity and metabolic adaptations." (PMID 40979718, 2025). "Seven factors – longer diabetes duration, older age, overweight/obesity, diabetes treatment modalities (oral antidiabetic drugs [OADs] and/or insulin), female gender, medication non-adherence, and the presence of dyslipidaemia – were reported by ≥10% of the studies." (PMID 41395632, 2025). "Among individuals with DM, 90%–95% are diagnosed with type 2 diabetes mellitus (T2DM), which is characterized by insulin resistance, relative insulin underproduction, and elevations in fasting and postprandial glycemia." (PMID 41561053, 2025). "For instance, insulin sensitizers (Thiazolidinediones and Biguanides), insulin secretagogues (Meglitinide and Sulfonylureas derivatives), dipeptidyl peptidase-4 (DPP-4) inhibitors, α-glucosidase inhibitors, and exogenous insulin have been extensively used to treat diabetes mellitus." (PMID 40722869, 2025). "Furthermore, SARS-CoV-2 can damage insulin-producing pancreatic cells, which can lead to hyperglycemia or diabetes, even in patients without the disease." (PMID 41009326, 2025). "Originally known as the main enzyme involved in the cleavage of insulin as well as other amyloidogenic peptides, such as the β-amyloid (Aβ) peptide, it eliminates Aβ’s neurotoxic effects—one of the hallmarks of Alzheimer’s disease (AD)—which shows the relationship between IDE, diabetes, and AD." (PMID 40943177, 2025). "Finally, we did not evaluate the severity of diabetes, endogenous insulin secretion, or treatment regimens." (PMID 41464593, 2025). "Back in 2019, researchers found that inulin-propionate ester, projected to selectively carry propionate to the colon, inulin, and cellulose were effective in improving insulin sensitivity for twelve adults with overweight or obesity but without diabetes, after 42 days of supplementation." (PMID 40507175, 2025). "When insulin-induced signaling does not work properly, it can lead to diabetes." (PMID 40603733, 2025). "In our cohort, elevated glycemic, lipemic, and insulin-related parameters in prediabetic individuals paralleled the observed increase in CCET, supporting the contribution of early metabolic dysregulation to corneal epithelial thickening prior to overt diabetes." (PMID 41464186, 2025).
diabetes (continued). "Due to the progressive nature of diabetes, the efficacy of therapy simplification may be impacted not only by diabetes-related factors, such as insulin requirement, glycated hemoglobin (HbA1c) level, and body weight (BW), but also by the disease duration." (PMID 40264573, 2025). "In addition, the American Diabetes Association’s standards of medical care for diabetes patients recommend that when medical nutrition therapy, exercise, and glucose monitoring are not successful at controlling blood glucose levels, insulin may be given as a last resort." (PMID 39910543, 2025). "Therefore, current research aims to identify the influence of diabetes on lipid profile, serum PSA, and endocrine factors such as insulin, IGF-1, and testosterone in prostate cancer and its association with progression, risk, and aggressiveness of prostate cancer." (PMID 41367482, 2025). "The presence of treatments (insulin, metformin, statins) and conditions (diabetes) that could potentially alter metabolism did not affect the arterial blood Eredox." (PMID 40424308, 2025). "This discrepancy may be explained by differences in experimental design, as TRIM72's negative effects on insulin signaling appear to be specific to models of severe diabetes where it exacerbates, rather than initiates, metabolic dysfunction." (PMID 41000062, 2025). "Thus, the pre-insulin age laid a conceptual foundation that would both advance and constrain future thinking: diabetes was metabolic, not immunological, and singular, not heterogeneous." (PMID 40725617, 2025). "Together, these findings suggest absence of insulin may be a primary driver of pancreas atrophy in diabetes." (PMID 41036139, 2025). "Lower BMI usually results from inadequate insulin replacement, which may predict non-adherence to diabetes management tasks (such as treatment adherence, blood glucose monitoring, and dietary intake) in children and adolescents with T1D." (PMID 40310133, 2025). "We have information about the presence of diabetes in our patients (and this was taken into account in the analysis), but not the full details of stop and start dates for insulin or other types of treatment, which could be a limitation of our study." (PMID 40424240, 2025). "The UK Prospective Diabetes Study estimated that, regardless of age, 10-15% of patients with a presumptive diagnosis of T2DM had underlying autoimmune diabetes, with 58% requiring insulin within 6 years of diagnosis." (PMID 41357182, 2025). "The possibility of providing dual mechanisms of reduced blood glucose via phytocannabinoid treatment, by both improved insulin sensitivity and glucose clearance as well as decreased SGLT2 transporter activity and renal glucose reabsorption, could serve as a comprehensive diabetes treatment." (PMID 40872492, 2025). "Of these, six studies used an HFD between 14 and 21 days; however, they did not provide any data on insulin sensitivity when confirming diabetes, with results reported after the end of the intervention (between 21 and 69 days), a period in which HFD consumption is maintained." (PMID 40426986, 2025). "It is based on a mathematical model of the glucose-insulin metabolism that integrates the following data: body mass (BM), age, sex, presence and type of diabetes, renal replacement therapy, serial blood glucose measurements, insulin therapy, non-nutritional calories, and the nutrition support." (PMID 40036206, 2025). "Given adequate glucose control maintained over a sufficient period during working hours, preventing qualified professionals with insulin-treated diabetes from receiving ATCO certification appears no longer appropriate, and it is necessary to reformulate the normative." (PMID 41007688, 2025). "Type 2 diabetes mellitus (T2DM) is complex and driven by several pathophysiological defects, often referred to as the "ominous octet," which includes impaired insulin secretion, insulin resistance, excessive hepatic glucose production, and other metabolic dysfunctions." (PMID 41426747, 2025).
diabetes (continued). "Routine self-monitoring of blood glucose in non-eligible patients, such as those with diabetes not treated with insulin, may lead to increased anxiety and depression scores and is associated with resource wastage." (PMID 41458677, 2025). "Thus, diabetes progression is not solely driven by insulin resistance or glucose toxicity but by a fundamental failure in β-cell organelle homeostasis." (PMID 40136648, 2025). "However, they stated that there had been no problems reaching the diabetes team whenever a need for an insulin or glucagon dose arose." (PMID 40310133, 2025). "Current treatments focusing primarily on insulin and metformin might not fully address the complex pathophysiology of diabetes." (PMID 41149695, 2025). "Interestingly, persons with diabetes using “non-insulin GLD only” and “insulin and non-insulin GLD” had lower all-cause mortality risks in both women and men compared to other HCS recipients." (PMID 41350985, 2025). "We examined whether declining insulin sensitivity (IS), independent of beta-cell function (BCF), is associated with diabetes progression." (PMID 41561051, 2025). "However, 23 (21%) discontinued insulin entirely, and 38 (35%) discontinued at least one non-insulin diabetes medication." (PMID 40700264, 2025). "Notably, this association remained significant even after adjustment for age, sex, diabetes duration, BMI, plasma triglycerides, CKD, LSM, time above the range (TAR) of glucose levels and daily insulin dose (adjusted model 1: beta coefficient = −0.223, 95% CI −0.324 to −0.121; p < 0.001)." (PMID 40083078, 2025). "For example, a study in Italy reported that the excessive prescription of SMBG strips contributed to cost overruns and resulted in some patients, particularly those with insulin-treated diabetes, not receiving a sufficient number of strips to adequately monitor their blood glucose levels." (PMID 41458677, 2025). "However, a 12-week blueberry intervention study demonstrated lower fasting blood insulin levels in a population with pre-diabetes and subjective cognitive decline while no additional changes in fasting blood glucose levels and HOMA-IR were noted." (PMID 38919390, 2024). "The RISE study demonstrated that the main predictor of worsening glycemia in adolescents with T2D or IGT was baseline β-cell dysfunction, and that neither metformin nor insulin plus metformin prevented deterioration in β-cell function in those with T2D or pre-diabetes, in contrast to adults." (PMID 38958831, 2024). "In the models with diabetes induced by diet or age, NMN treatment could effectively improve impaired glucose tolerance through the enhancement of NAD+ levels, promotion of insulin secretion or insulin sensitivity." (PMID 38653987, 2024). "Five participants with previously diagnosed type 2 diabetes were already on insulin before admission and, with all having diabetes of prolonged duration and HbA1c >86 mmol/mol (10%), no attempt was made to wean them off insulin; these individuals are not included in our results." (PMID 38240751, 2024). "Thus, it is likely that sarpogrelate may exert its effects on diabetes through both the blockade of 5-HT2A receptors and the release of insulin from the pancreas." (PMID 39057635, 2024). "While the initial diabetes education materials encouraged regular blood sugar testing and adherence to diabetes medications, no adaptations were made specifically for those who might be taking insulin." (PMID 38212794, 2024). "Given that the link between brain insulin signaling and diabetes remains unclear, we also tested whether diabetes was related to cognition in this small sample of persons with and without diabetes." (PMID 38029396, 2024). "In diabetes, the pancreas does not produce any insulin at all or uses it improperly." (PMID 39766863, 2024). "That is, whether insulin-treated or non-insulin-treated patients, it is not the values of these variables that contribute more or less to the knowledge of people with diabetes." (PMID 38525337, 2024).